TMEM50B (transmembrane protein 50B)
Synonyms: C21orf4; HCVP7TP3
Tractability: Antibody: UniProt predicts a signal peptide or a membrane-spanning region. PROTAC: its protein half-life has been measured.
Gene: Protein-coding gene on chromosome 21 (33,432,485 to 33,479,974, reverse strand). Ensembl gene ENSG00000142188.
Subcellular location: Endoplasmic reticulum membrane; Golgi apparatus membrane
Subcellular location (Human Protein Atlas): Nucleoli fibrillar center
Gene Ontology:
Molecular function: protein binding
Biological process: late endosome to vacuole transport via multivesicular body sorting pathway
Cellular component: endoplasmic reticulum; plasma membrane; endoplasmic reticulum membrane; Golgi membrane
Genetic constraint (gnomAD): Loss-of-function variants: 10 observed, 17.76 expected, observed/expected ratio (o/e) 0.56, 90% interval 0.35 to 0.95. The upper end of that interval is the gene's LOEUF score, 0.95, which puts it in group 4 of 6, group 1 being the genes least tolerant of losing a copy. Missense variants: 121 observed, 161.09 expected, observed/expected ratio (o/e) 0.75, 90% interval 0.65 to 0.87. Synonymous variants: 57 observed, 54.13 expected, observed/expected ratio (o/e) 1.05, 90% interval 0.85 to 1.31.
Homologues: Orthologues: chimpanzee TMEM50B (100% identical), pig TMEM50B (100% identical), rabbit TMEM50B (99% identical), mouse Tmem50b (98% identical), rat Tmem50b (98% identical), guinea pig TMEM50B (97% identical), dog TMEM50B (92% identical), tropical clawed frog tmem50b (88% identical), macaque TMEM50B (65% identical), Caenorhabditis elegans Y74C10AL.2 (50% identical), Drosophila melanogaster CG15012 (35% identical). Paralogues in human: TMEM50A (69% identical).
Diseases named in the same sentence as TMEM50B in open-access papers:
TMEM50B is named in the same sentence as 9 diseases in open-access papers, as found by Europe PMC text mining. Sharing a sentence is not in itself a finding about the gene and the disease. The quoted sentences say what the papers report.
Down syndrome (3 papers, 2016 to 2025). "Located on chromosome 21, TMEM50B has been implicated in the neurophenotypes of Down syndrome due to being one of a few genes upregulated in model systems of Down syndrome, particularly in the cerebellum during development." (PMID 41457042, 2025). "In a study that assesses biomarkers to investigate the etiology of Down syndrome, TMEM50B was found to be upregulated two fold in Down syndrome samples compared to normal." (PMID 27030248, 2016).
psoriasis (1 paper, 2022). An autoimmune condition characterized by red, well-delineated plaques with silvery scales that are usually on the extensor surfaces and scalp. "Some psoriasis loci showed a substantial single-tissue eQTL, primarily in the cardiovascular system (artery coronary: rs240993/KIAA1919, rs9808753/TMEM50B, heart left ventricle: rs11053802/KLRC4, heart left ventricle: rs11053802/KLRK1, rs5063/CLCN6, rs1050414/HLA-B, rs2778031/SPIN1)." (PMID 36320003, 2022).
TMEM50B also shares sentences with these, for which no sentence is quoted: Alzheimer disease (1 paper); atherosclerosis (1); behavioral disorders (1); Intellectual disability (1); malignant tumors (1); neurodegenerative disease (1); thyroid nodule (1).